FOLR1 (folate receptor alpha)
Diseases named in the same sentence as FOLR1 in open-access papers (continued):
Sharing a sentence is not in itself a finding about the gene and the disease.
tumor (continued). "Cisplatin further enhanced the positive correlation between the area of tumor colonies and gene expression of PGE2S, EGFR, FOLR1, EP3, COX2, and VEGFA in cancer cells, highlighting the importance of these genes in treatment resistance." (PMID 33671869, 2021). "Using an ectopic xenograft model with high expression of FOLR1 and MSLN, complete tumor eradication was achieved in one of five treated mice in the Tandem-CAR group, with tumor outgrowth observed in the single-target CAR-T groups." (PMID 34803504, 2021). "As an example, CARs of mesothelin scFv-CD3z and folate receptor alpha (FRα) scFv-CD28 have been introduced simultaneously, resulting in an improved tumor trafficking and reduction of toxicity." (PMID 34830003, 2021). "Using an anti-CD3ε mAb, anti-FOLR1 mAb, and anti-MSLN mAb, we examined the distribution of T cells and expression of FOLR1 and MSLN in tumor samples from mice by IHC analysis." (PMID 34803504, 2021). "The average tumor volume in the Control-T group increased to 711.2 mm3, whereas those in the MSLN-CAR, FOLR1-CAR, and Tandem CAR-T groups were 227.1 mm3, 21.7 mm3, and 5.0 mm3, respectively (p <0.0001)." (PMID 34803504, 2021). "Specifically, there is a 48% to 76% probability of near-completely eliminating tumor by targeting FOLR1 or MSLN alone, while targeting FOLR1 and MSLN simultaneously was predicted to kill more than 88% of cancer cells based on a cohort of 160 OVs." (PMID 34803504, 2021). "In order to analyze the kinetics of T-cell-mediated cytotoxicity mediated by the Prot-FOLR1-TCB, we investigated tumor cell growth for MDA-MB-231 NucLight red cancer cells (medium FOLR1 expression) during coincubation with PBMCs and the Prot-FOLR1-TCB." (PMID 32581215, 2020). "The overexpression of FOLR1 or FR-α was previously confirmed on colon DLD-1, while in the epidermal squamous carcinoma A431 tumour cell line FOLR1 expression was reduced." (PMID 32503320, 2020). "Quantitative analysis of Western blotting analysis showed that FOLR1 and MTRR have the highest expression in OC tissues, while DHFR has the highest expression in benign tumor tissues." (PMID 31049278, 2019). "To compare conventional and chemically programmed biAbs side-by-side, we chose folate receptor 1 (FOLR1; also known as folate receptor α) as a tumor cell surface receptor." (PMID 31497024, 2019). "In CRC, the main molecular markers available for active targeting are the carcinoembrionic antigen (CEA), the folate receptor alpha (FRα), and the epidermal growth factor receptor (EGFR and HER2) present onto the tumor cells." (PMID 31662751, 2019). "As expected, most of the tumor samples analyzed (> 90%) expressed very high levels of CA125, FOLR1, EPCAM and MUC-1 and elevated levels of Her-2/neu, similarly to OVCAR-3 cell line." (PMID 27323861, 2016). "Most of the tumor samples analyzed (> 90%) expressed very high levels of CA125, FOLR1, EPCAM and MUC-1 and intermediate levels of Her-2/neu, similarly to the OVCAR-3 cell line." (PMID 27323861, 2016). "More than 90% of tumor samples expressed very high levels of CA125, FOLR1, EPCAM and MUC-1 and elevated levels of Her-2/neu, similarly to OVCAR-3 cell line." (PMID 27323861, 2016). "Expression of FOLR1, FPGS, MLH1 and TYMS (each p<0.0001) differed significantly between all four tumor types." (PMID 27064343, 2016). "A ratio between FOLR1 and SLC19A1 was calculated to identify the prominent uptake mechanism for each tumor subtype." (PMID 27064343, 2016). "By qPCR, 11 out of 33 (33.3%) cancer samples displayed FRα gene (FOLR1, chromosome 11q13.3) amplification when compared with the corresponding non-tumor counterparts." (PMID 23144806, 2012). "The folate receptor 1 (FOLR1) and Epcam proteins were considerably decreased in exosomes that were derived from the serum of invasive non-functional PitNETs, thereby indicating their potential role as biomarkers regarding tumor invasiveness." (PMID 40699709, 2025).
tumor (continued). "FOLR1 expression was scored using the VENTANA FOLR1 (FOLR1-2.1) RxDx Assay, which indicated that the majority of FOLR1 localization occurred in the epithelial tumor cells rather than stromal regions." (PMID 40029935, 2025). "Overall, the addition of FOLR1 CAR-T cells had a major impact on the composition of the infiltrating immune cells in tumor areas rather than in stroma areas, while the addition of UTD T cells increased the myeloid cell infiltration in the whole tissue slice." (PMID 40779497, 2025). "Using RTCA co-culture assays with Vγ9Vδ2 T cells and tumor cell lines, we identified “Evobodies” that exhibit a strong therapeutic window and high potency against FOLR1-positive cells, while sparing healthy, FOLR1-negative tissue." (PMID 40755782, 2025). "Other FOLR1-targeting agents such as FDA-approved mirvetuximab soravtansine also did not reveal toxicities specific to off-tumor FOLR1 targeting." (PMID 40919994, 2025). "FOLR1 is an attractive target of interest in many solid tumors due to its expression on the surface of tumor cells and low to no expression on normal tissues." (PMID 40919994, 2025). "Furthermore, FOLR1 and TSLC1 work together to mediate MEK/ERK activation in nasopharyngeal carcinoma (HONE1) cells, thereby inhibiting tumor invasiveness." (PMID 41283276, 2025). "Moreover, anti-FOLR1 CAR candidates A and E showed pronounced homing to bone marrow and spleen, and superior tumor infiltration compared to other CAR candidates." (PMID 38254822, 2024). "Interestingly, anti-FOLR1 candidates A and E showed an increased presence of human CD45, CAR+, and CD8 T cells in the tumor tissues." (PMID 38254822, 2024). "Moreover, our FOLR1 CAR showed antigen-dependent cytokine release and pronounced tumor infiltration." (PMID 38254822, 2024). "Anti-FOLR1 candidate G also showed no detectable proliferation and no detectable tumor infiltration by CAR+ and CD8 cells." (PMID 38254822, 2024). "Interestingly, we observed an increase in IL-9 at day 7 post CAR T cell injection for anti-FOLR1 CAR candidates A and E, correlating with the faster tumor-killing kinetics." (PMID 38254822, 2024). "The pan-tumor panel identified nine tumor cell subsets, which were defined as being negative for CD45 and CD56, but expressing at least one of the three markers, namely, EpCAM, FOLR1, and CD24." (PMID 37894472, 2023). "However, the mechanism of FOLR1 upregulation in HCC cells is still unclear, especially in the tumour environment." (PMID 38057830, 2023). "The tumor/stromal cells included one CD56+fibroblast population and nine CD45−CD56−cell populations, which were distinguished by the expression of the three select tumor markers, namely, EpCAM, FOLR1, and CD24." (PMID 37894472, 2023). "In addition, CAR-T targeting carcinoembryonic antigen (CEA), HER2, CLDN18.2, FOLR1, c-Met, CD133, and CDH17 had a significant anti-tumor effect in the corresponding target-positive GC mouse model and the tumor appeared partially or even complete regression." (PMID 36225938, 2022). "Among the tumor cell clusters identified, two separately clustered categories of cells were observed: tumor cells expressing EpCAM, FOLR1, or both, with high expression of CD47 and those without high expression of CD47 (total clusters n = 10)." (PMID 33670410, 2021). "Compared with Tandem-CAR and FOLR1-CAR T cells, MSLN-CAR T cells showed lower antitumor activity and only achieved a transient reduction in the tumor burden (p <0.001, p <0.01), which was consistent with the total fluorescence intensity data (p <0.0001, p <0.05)." (PMID 34803504, 2021). "FOLR1 can internalize folates into the cells, which is crucial to DNA repair and synthesis, and mediate the activation of pro-oncogene STAT3, which contributes to angiogenesis, tumor proliferation, and metastasis." (PMID 34124126, 2021).
tumor (continued). "We observed maximum tumor cell cytotoxicity in all cases except when the low-affinity FolR1-TCB was incubated with the low FolR1-expressing cell line, which did not result in either measurable tumor cell cytotoxicity or cytokine release." (PMID 34862519, 2021). "Wing and colleagues showed that CAR T cells targeting folate receptor alpha (FR-α) successfully infiltrated xenografted tumors, but failed to achieve complete responses, presumably due the presence of FR-α-negative cancer cells induced by tumor escape." (PMID 32664210, 2020). "In addition, the study of the potential modulation of the soluble folate receptor alpha (FOLR1) by treatment with the synthesized materials has been carried out using OVCAR-3, DLD-1, A2780 and A431 tumour cell lines." (PMID 32503320, 2020). "To identify the tumor cells and non-tumor lung cells, we first mapped the expression of six genes (FOLR1, AGR3, and SFTPD for normal hung lung cells, and EPCAM, MDK, and SOX4 for cancer cells) to each cluster to identify the cell types in our study." (PMID 32549766, 2020). "To determine whether the FOLR1-CAR Jurkat cells specifically recognize the FOLR1-positive cells, we used KB cells which are one of the subline of HeLa cells (keratin forming tumor cell line HeLa) and are commonly used in FOLR1 studies." (PMID 29874279, 2018). "Lastly, we included folate receptor-alpha (FR-α), which is expressed in several tumor types but not in normal ovarian tissue." (PMID 26946151, 2016). "FOLR1 expression did not correlate to common clinicopathological parameters such as tumor stage and nodal status." (PMID 25816016, 2015). "One of the mice in the CART-treated arm developed weight loss by day 168 and upon necropsy was found to have a FOLR1-expressing abdominal tumor, presumed to have developed from engrafted non–GFP-tagged tumor cells, explaining the lack of emitted radiance on IVIS imaging." (PMID 40919994, 2025). "Importantly, we show that our tumor-engaging molecules avoid premature immune cell activation, degranulation, and cytokine release in the absence of FOLR1-positive tumor cells." (PMID 40755782, 2025). "FH FOLR1-CART activation was additionally confirmed by measurement of proinflammatory cytokines IL-2, IFN-γ, and TNFα detected in 1:1 co-culture supernatant collected at 24 hours with no or minimal cytokines detected in the supernatant from NT T cells co-cultured with tumor cells." (PMID 40919994, 2025). "In this study, we observed significantly higher FOLR1 levels in patients with TGCTs who achieved unfavorable responses to first-line therapy (other than complete remission and/or partial remission with negative serum tumor markers)." (PMID 39996761, 2025). "Thus, as FOLR1 may not be expressed in non-tumour tissue, it is still a valid target that warrants further investigation." (PMID 34830751, 2021). "In line with the results from the cytotoxicity experiments with FOLR1 KO tumor cells described earlier, ETA-067 did not induce the premature, tumor anchor-independent degranulation in pre-activated Vγ9Vδ2T cells." (PMID 40755782, 2025). "Albeit, the FOLR1 expression in mice has not fully been investigated yet, mouse–human cross-reactive binders—as characterized in this study—could be a valuable tool to address on-target, off-tumor expression of FOLR1 in murine tissue and potential on-target, off-tumor related toxicity in mice." (PMID 39594628, 2024). "In order to show that the Prot-FOLR1-TCB can be activated by human patient-derived samples expressing FOLR1 as a tumor target antigen, we set up a method to analyze tumor samples without digestion to exclude artefacts coming from tumor digestion." (PMID 32581215, 2020).
tumor (continued). "Similar to the biomarker HE4, peptides for Urokinase plasminogen activator surface receptor (UPAR) and folate-receptor-alpha (FOLR-a) were found in the swab and Pap test fluid, but not in the tumor tissue (although only a single peptide for FOLR-a was found in the Pap test fluid)." (PMID 33413078, 2021). "Notably, the antitumor activity of Tandem CAR-T cells exceeded that of FOLR1-CAR T cells (p <0.05), and the tumor in one mouse was completely eradicated at day 28; the tumor did not recur through the end of the experiment." (PMID 34803504, 2021). "The dose–response analysis of low-affinity FolR1-TCB targeting high- and low-expression cells showed that there was only minimal tumor lysis and no IL6 release in the low-expression cell line, suggesting that low-expression tissues would be minimally targeted by the low-affinity variant." (PMID 34862519, 2021). "Although no formal validation of FOLR1 as an LSC marker has been undertaken, preclinical modeling of STRO-002, an antibody-drug conjugate (ADC) against FOLR1 and, separately, a FOLR1-specific chimeric antigen receptor T cell (CAR-T), showed promising anti-tumor efficacy." (PMID 38137469, 2023).
cancer (201 papers, 2009 to 2026). A tumor composed of atypical neoplastic, often pleomorphic cells that invade other tissues. "A growing number of signaling pathways that control the development of cancer and cellular processes have been linked to folate receptor 1 or FOLR1." (PMID 41283276, 2025). "MOv18 IgE, the first IgE antibody to enter the clinic, targets the cancer-associated antigen Folate Receptor-alpha (FRα), known to be overexpressed in several cancers including ovarian, endometrial, Triple-negative breast cancer and lung." (PMID 39934835, 2025). "Complementary transcriptomic analyses from the Genotype-Tissue Expression (GTEx) and Cancer Genome Atlas (TCGA) public databases further revealed that FOLR1, the gene encoding FRα, is overexpressed in numerous cancers relative to normal tissues." (PMID 41038820, 2025). "FOLR1 has been reported to be overexpressed in multiple cancers of epithelial origin, and overexpression of FOLR1 is associated with cancer progression and a poor patient prognosis." (PMID 40038575, 2025). "FRα, encoded by the FOLR1 gene, has been focused on due to its high expression in several cancer types including OC, and is highly expressed in approximately 50-80% of patients with OC." (PMID 39061184, 2024). "In this study, we incorporated FA as a moiety against cancer cells with folate receptor alpha (FRα), a membrane-anchored receptor encoded by the FOLR1 gene that is essential for folate transport into cancer cells." (PMID 40115434, 2024). "Studies have revealed that the upregulation of FOLR1 is associated with sorafenib resistance in cancer cells." (PMID 38057830, 2023). "The stimulation of cell replication was found to be dependent on the C. elegans folate receptor ortholog, FOLR-1, an intriguing finding as the expression of the human folate receptor, FRα is associated with poor prognosis in several cancers." (PMID 32138646, 2020). "Promising targeted treatments and immunotherapy strategies in oncology and advancements in our understanding of molecular pathways that underpin cancer development have reignited interest in the tumor-associated antigen Folate Receptor alpha (FRα)." (PMID 27248175, 2016). "Folr1–3 are known to bind folate by a newly described mechanism, and the heightened expression of Folr1 and Folr2 in disease-causing cells in cancers and inflammatory diseases has led to extensive research into folate receptor-targeted therapies." (PMID 27019721, 2015). "Membrane-bound FOLR1 has generated much interest as a diagnostic and chemotherapeutic target on the basis of observations of high expression in some cancers relative to healthy tissue." (PMID 24810481, 2014). "Serum concentrations of the tumor-associated folate receptor 1 (FOLR1) protein may be a marker for early cancer detection, yet concentrations have also been detected in cancer-free women." (PMID 24810481, 2014). "Designing CAR-T cells that can differentiate between cancer cells and cancer-free cells is essential to lower the risk of harm, apart from looking for antigens with limited expression on normal cells like folate receptor 1 (FOLR1) and tumor-associated glycoprotein 72 (TAG72)." (PMID 37834768, 2023). "Moreover, the expression of FOLR1 is known to be associated with the malignant potential of cancer." (PMID 33535554, 2021). "Folate receptor alpha (FRα)has emerged as a promising target for cancer therapy due to its pronouncedoverexpression in a variety of epithelial cancers." (PMID 41307319, 2025). "Folate receptor alpha is often overexpressed in cancer cells, as they have an increased need for folate to support their rapid growth and division." (PMID 40830177, 2025). "All of these results demonstrate that FOLR1 is a multifunctional receptor that influences cancer biology and cell fate determination by combining intracellular signaling, transcriptional regulation, and extracellular folate availability." (PMID 41283276, 2025).